MIR634 (microRNA 634)
Synonyms: hsa-mir-634; MIRN634
Gene: MicroRNA gene on chromosome 17 (66,787,072 to 66,787,168, forward strand). Ensembl gene ENSG00000207943.
Homologues: Orthologues: chimpanzee ptr-mir-634 (100% identical).